CXCL8 (C-X-C motif chemokine ligand 8)
Diseases named in the same sentence as CXCL8 in open-access papers (continued):
Sharing a sentence is not in itself a finding about the gene and the disease.
temporal lobe epilepsy (1 paper, 2025). A localization-related (focal) form of epilepsy characterized by recurrent seizures that arise from foci within the temporal lobe, most commonly from its mesial aspect. "Patients with temporal lobe epilepsy (TLE) exhibit increased serum CXCL8 levels." (PMID 40243443, 2025).
transient cerebral ischemia (1 paper, 2025). "In rabbits exposed to transient cerebral ischemia, CXCL8 levels increased 6 h after reperfusion." (PMID 38861234, 2025).
tumor (4,600 papers, 1995 to 2026). "Higher MIF levels were further associated with larger tumor dimension, while IL-8/CXCL8 was associated with increased bilirubin level and recent weight loss (p < 0.05)." (PMID 42122077, 2026). "In summary, IL-6, TNF-α, IL-17A, and CXCL8 (IL-8) emerge as the cytokines most strongly linked to promoting anoikis resistance in tumor cells, activating survival pathways like NF-κB, STAT3, and AKT/ERK." (PMID 41596231, 2026). "Tumor-associated macrophages (TAMs) facilitate metastasis of PTC cells via secretion of CXCL8/interleukin (IL)-8 and paracrine interaction with CXCR1/2." (PMID 40313970, 2025). "Recent findings indicate that CXCL8 production by cancer cells in vitro is regulated at multiple levels and is strongly influenced by the tumor’s genetic profile, particularly mutations in genes such as BRAF and Phosphatase and Tensin Homolog (PTEN)." (PMID 40943634, 2025). "CXCL8 is primarily recognized for attracting and activating immune cells such as neutrophils, monocytes, and T cells, and is implicated in various tumor progressions." (PMID 40678806, 2025). "This dual function is well documented in melanoma, which expresses chemokines such as CCL2, CCL5, CXCL1, CXCL2, CXCL3, and CXCL8 which have been implicated in tumor growth and progression." (PMID 40943634, 2025). "Tumor-secreted CCL5 and CXCL8 also play roles in recruiting monocytes, neutrophils, and other leukocytes, which can differentiate into TAMs and tumor-associated neutrophils (TANs), both of which can assume pro-tumorigenic roles." (PMID 40365348, 2025). "CXCR2 is not only activated by CXCL1 but also by several other CXC chemokines, including CXCL2, CXCL3, CXCL5, CXCL6, and CXCL8, all of which are closely associated with cancer progression and the tumor microenvironment." (PMID 40490643, 2025). "Heightened levels of CXCL8 along with overexpression of CXCR1 or CXCR2 have been implicated in promoting tumor cell proliferation and metastasis through the activation of PI3K/AKT and ERK1/2 MAPK signaling pathways." (PMID 40124384, 2025). "Our study demonstrates that resistance of mesenchymal-like TNBC cells is associated with down regulation of BIRC5 (survivin) and upregulation of CXCL8/IL-8 and M-CSF while that of epithelial tumor cells is associated with upregulation of CTSS, MCP-1 and DKK-1." (PMID 41279138, 2025). "The identification of malignant cells in the fibroblast subpopulation of Galectin 7B and CXCL8 suggests that abundance in tumor tissue is associated with poor prognosis." (PMID 41403916, 2025). "In TNBC, CXCL8 derived from tumor-associated adipocytes regulates the immunosuppressive microenvironment and promotes tumor progression by up-regulating the expression of CD274 and inhibiting T cell infiltration." (PMID 40256431, 2025). "C–X–C motif chemokine ligand 8 (CXCL8) is highly expressed in tumor-associated adipocytes and promotes EMT of TNBC through the PI3K/AKT pathway, thereby promoting the growth and metastasis of TNBC71." (PMID 40256431, 2025). "The CXCL8/IL-8 axis, which has been studied most extensively for its role in proinflammatory processes, has been implicated in tumor growth and metastasis in several cancers." (PMID 39905539, 2025). "Using multiple KRAS-driven human LUAD cell lines, our work demonstrates that STK11 loss results in altered tumor-intrinsic cytokine expression, including but not limited to IL-6, CXCL8 and CXCL2." (PMID 37968341, 2024). "Elevated expression of CXCL8 has been indicated in endothelial cells, infiltrating neutrophils, tumor-associated macrophages, and cancer cells." (PMID 38673838, 2024). "One such protein is CXCL8 (IL-8), a chemotactic cytokine for granulocytic cells implicated in tumor promotion." (PMID 38900577, 2024). "Inflammatory cytokines were also significantly overexpressed in NSCLC tumor tissues, among which CXCL8 (encoding C-X-C motif chemokine ligand 8) showed the most significant changes in both in the transcriptome sequencing data and tumor tissues." (PMID 38405671, 2024).
tumor (continued). "CXCL8 overexpression has also been described in NSCLC as a cause of tumor invasiveness and has been highlighted as a potential therapeutic target in different cancers." (PMID 38674080, 2024). "The diagnostic sensitivity, NPV, and the AUC of CXCL8 were higher than those of conventional tumor markers." (PMID 38673838, 2024). "The IL1’/CXCL8/CXCR2 axis has been implicated in several tumor types and plays a role in neutrophil recruitment." (PMID 38358352, 2024). "Accordingly, the PubMed, Wanfang, Scopus and Web of Science databases were searched for articles published until July 20, 2023 using the keywords ‘IL-8’ or ‘interleukin-8’ or ‘CXCL8’, ‘polymorphism’ and ‘cancer’ or ‘tumor’." (PMID 38807156, 2024). "CXCL8 can recruit tumor-associated neutrophils, which partly impair the cytotoxic effects of CD8+ T cells in a contact-dependent manner." (PMID 37765018, 2023). "The literature associates CXCL8 with tumor growth, chemoresistance, and epithelial-to-mesenchymal transition (EMT)." (PMID 36831112, 2023). "In a recent study, the diagnostic potential of C-X-C motif ligand 8 (CXCL-8) levels in the sera of patients was compared with classical tumor markers (CEA and SCC-Ag) and the well-established marker of inflammation—C-reactive protein." (PMID 37046658, 2023). "Results showed that tumor-associated macrophages are the major source of CXCL8 in the tumor microenvironment." (PMID 37765018, 2023). "In this study, we explored the expression profile of CXCL8 in the tumor microenvironment using previous databases and confirmed that tumor-associated macrophages are the major source of CXCL8." (PMID 37765018, 2023). "Results showed that tumor-associated macrophages and antigen-presenting fibroblasts have significantly higher CXCL8 expression than cancer-associated myofibroblasts." (PMID 37765018, 2023). "CXCL8, mainly secreted by tumor-associated macrophages, can activate the NF-κB signaling pathway in endothelial cells via a CXCR2-dependent manner." (PMID 37765018, 2023). "In contrast, in CALB1-expressing tumors, transcription of the same mediators was minimal in cancer cells and instead was found in myeloid cells (CXCL2, CXCL8) and/or tumor-associated fibroblasts (CXCL5, CXCL6)." (PMID 37192000, 2023). "In Ras-driven cancers, CXCL8 attracts tumour-associated neutrophils (TANs) to the tumour immune microenvironment, and TANs secrete arginase 1 to favour immune suppression." (PMID 37919768, 2023). "Among patients with current metastases, higher CXCL8 levels were associated with increased tumor load (p < 0.0001) and more rapid growth (p = 0.0114)." (PMID 37370728, 2023). "CXCL8 has been implicated in angiogenesis, metastasis-related tissue remodeling, and tumor cell susceptibility to chemotherapies." (PMID 36769510, 2023). "Tumor-associated macrophages with protumor and inflammatory characteristics (VEGFhigh/CXCL8+/IL1β+) are found in solid ovarian tumors." (PMID 37765018, 2023). "Emerging investigations have highlighted several novel mechanisms that are associated with the role of CXCL8 in cancer cell invasion and migration, including tumor heterogeneity, formation of feedback loop, and interacting with TME." (PMID 35372515, 2022). "This study aimed to investigate the prognostic role of CXCL8 within the tumour epithelium and tumour‐associated stroma utilising a retrospective cohort of stage I–IV CRC patients undergoing surgery with curative intent." (PMID 35879507, 2022). "Knockdown of ALKBH5 in GBM cells significantly inhibited hypoxia-induced recruitment and immunosuppression of tumor-associated macrophages in allograft tumors, and CXCL8/IL8 expression and secretion were significantly suppressed." (PMID 35711459, 2022). "At present, the association between CXCL8 and tumor immunity and immunotherapy deserves much more attention." (PMID 36532065, 2022).
tumor (continued). "Interleukin-8 (CXCL8) is considered as a promising pro-inflammatory marker of carcinogenesis associated with tumor angiogenesis, invasion through activation of the epithelial–mesenchymal transition, secondary neutrophil chemotaxis into the tumor zone." (PMID 36517518, 2022). "CXCL8 has been revealed to bind to its receptor and then trigger many downstream signaling cascades, among which NF-κB signaling is associated with tumor VM formation." (PMID 35321317, 2022). "Chi‐squared tests were performed to determine any association between stromal CXCL8 expression and clinical characteristics/histological tumour features." (PMID 35879507, 2022). "The results revealed that the positive expression of CXCL8 was associated with the N stage and the formation of intravascular tumor thrombus." (PMID 35845924, 2022). "For example, TAMs secret CXCL8 triggering EGFR signaling of tumor cells which is the leading cause of drug resistance in refractory CRC with KRAS or BRAF V600E mutation." (PMID 35186730, 2022). "A plethora of literature indicates that CXCL8 is involved in the maintenance of cancer stem cells (CSCs) which is always associated with tumor development and progression, treatment resistance and used to explain heterogeneity in solid tumors." (PMID 35372515, 2022). "Both trials further suggest that greater CXCL8 expression in tumor is associated with higher plasma CXCL8 level, an immunosuppressive myeloid-enriched TME, and T cell suppression." (PMID 35372515, 2022). "The expression of CXCL8 was positively associated with tumor stage, angiogenesis, and metastasis of PCa, and the elevated CXCL8 expression level was correlated with loss of AR expression." (PMID 36275733, 2022). "This study has strongly implicated CXCL8 mRNA expression within the tumour‐associated stroma as a marker of poor prognosis in CRC." (PMID 35879507, 2022). "Expression and secretion of CXCL8/IL-8 results in an immunosuppressive tumor microenvironment (TME) by recruitment of tumor-associated macrophages (TAM) leading to tumor progression." (PMID 36009578, 2022). "According to the results of IHC and the clinical data of related patients, a highly significant association between the expression of CXCL8 and the N stage (p = 0.007) and intravascular tumor thrombus (p = 0.032) was observed." (PMID 35845924, 2022). "Numerous cell types can produce CXCL8 including epithelial cells, endothelial cells, tumour‐associated macrophages, cancer‐associated fibroblasts (CAFs), and tumour cells themselves." (PMID 35879507, 2022). "In the present study, high expression of CXCL8 within the stroma was significantly associated with adverse histological features including high presence of tumour buds, stromal invasion, and moderate Ki67 proliferation index." (PMID 35879507, 2022). "Many investigations have indicated that CXCL-8 plays an important role in tumor angiogenesis and invasion and is linked with distant metastases in CRC." (PMID 36567905, 2022). "Current research has shown that CXCL3, CXCL5, and CXCL8 were CXC chemokines strongly associated with tumor angiogenesis." (PMID 35795552, 2022). "Concerning neoplastic diseases, non-small cell lung cancer, and gastric cancer have been proposed to be associated with CXCL8 SNPs." (PMID 33763088, 2021). "Other studies have indicated that high CXCL8 expression in HCC tissues was significantly associated with tumor size, differentiation, metastasis, poor overall survival, disease-free survival, and an increased risk of recurrence and mortality." (PMID 34680563, 2021). "CXCL8 chemoattractant myeloid-derived suppressor cells and tumor-associated neutrophils in the tumor microenvironment are associated with immune suppression." (PMID 34640631, 2021).
tumor (continued). "The combined measurements of CXCL8 with classic tumor biomarkers increased the diagnostic sensitivity up to 89%, when CXCL8 was analyzed together with CA19-9." (PMID 34680333, 2021). "The serum concentrations of both CXCL8 and CXCR2 were found to be elevated in EC patients, suggesting the significance of CXCL8 as a potential diagnostic tumor marker in EC." (PMID 33390169, 2021). "IL-8 is coded by CXCL8 gene, SNPs of which have been shown to be linked to infectious, autoimmune, and neoplastic diseases." (PMID 33763088, 2021). "Tumour-associated neutrophils are also able to produce CXCL8, thus creating a feedback loop for further neutrophil recruitment." (PMID 34830780, 2021). "CXCR1 and CXCR2 are receptors for IL-8 (CXCL8), an inhibitory chemokine involved in recruitment of tumor-associated neutrophils or myeloid derived suppressor cells (MDSCs), tumor proliferation and angiogenesis." (PMID 33746981, 2021). "We compared the diagnostic characteristics of CXCL-8 with those of the classical tumor markers for CRC." (PMID 34071492, 2021). "Emerging studies have revealed that a high level of systemic and tumour-associated CXCL8 is associated with reduced responses to immune checkpoint inhibitors in several types of cancer, including NSCLC50,51." (PMID 34381028, 2021). "IL-17 induces the secretion of CCL2, CXCL1, CXCL5, CXCL6, and CXCL8 from several types of cells that infiltrate the tumor, and subsequently, it recruits myeloid-derived suppressor cells, including tumor-associated macrophages." (PMID 32756356, 2020). "In the present study, we compared the diagnostic characteristics of CXCL-8 with the classical tumor markers for CRC." (PMID 32192002, 2020). "Similar to IL-6, the CXCR2 ligand IL-8, also known as CXCL8, has been associated with inflammation, tumour growth and angiogenesis." (PMID 33116132, 2020). "When compared to clinicopathological variables, a higher CXCL8 expression score was associated with higher T category and tumor grade." (PMID 32201645, 2020). "A prime example is chemokine CXCL-8, which has demonstrated to be involved in tumor angiogenesis and linked with promoting distant metastases in many malignancies, including CRC." (PMID 32192002, 2020). "The results showed that a high expression of CXCL8 in tumour tissues was associated with a high infiltration of TAMs, high expression of VEGF and MMP9, and a low expression of E-cadherin." (PMID 32201645, 2020). "A number of studies have demonstrated CXCL-8 expression on endothelial cells, tumor-associated macrophages, and cancer cells, including CRC." (PMID 32192002, 2020). "According to our knowledge, the present study is the first to compare the diagnostic characteristics of CXCL-8 with the well-established tumor markers (CEA and SCC-Ag) and the marker of inflammation—CRP in the sera of OC patients." (PMID 30820705, 2019). "The roles of IL-6 and CXCL8 in cancer are often associated with increased tumor cells proliferation, recruitment of MDSCs, angiogenesis, tumor cells stemness." (PMID 30832219, 2019). "The diagnostic specificity of CXCL-8 levels (73%) was lower than that of the classical tumor markers and CRP." (PMID 30820705, 2019). "The percentage of elevated concentrations and the most important diagnostic criterion, AUC of CXCL-8, was higher than the AUCs of the classical tumor markers." (PMID 30820705, 2019). "It has been shown that high levels of chemokines CCL3, CCL4, and CXCL8 in pre-treatment tumor specimens were associated with worse patient overall survival after anti-CTLA4 and Carboplatin/paclitaxel treatment in melanoma." (PMID 30873179, 2019). "Multiple studies associated the expression of CXCL8 with poor clinicopathological features including poor differentiation, advanced tumor stage, cancer cell proliferation, and angiogenesis." (PMID 29808619, 2018). "This is in agreement with our finding that increased levels of tumor CXCL8 are associated with decreased survival." (PMID 29850390, 2018).